SHBG (sex hormone binding globulin)
Description:
Functions as an androgen transport protein, but may also be involved in receptor mediated processes. Each dimer binds one molecule of steroid. Specific for 5-alpha-dihydrotestosterone, testosterone, and 17-beta-estradiol. Regulates the plasma metabolic clearance rate of steroid hormones by controlling their plasma concentration.
Synonyms: SBP; ABP; TeBG; MGC126834; MGC138391
Tractability: Small molecule: a structure with a bound ligand is known; a high-quality ligand is known; it has a high-quality binding pocket; it belongs to a druggable protein family. Antibody: UniProt places it where antibodies can reach, with medium confidence; UniProt predicts a signal peptide or a membrane-spanning region; its Gene Ontology location is reachable by antibodies, with medium confidence. PROTAC: a small molecule that binds it is known.
Target class: Secreted protein
Chemical probes: NSC-659853, PRASTERONE
Gene: Protein-coding gene on chromosome 17 (7,613,946 to 7,633,469, forward strand). Ensembl gene ENSG00000129214.
Subcellular location: Secreted
Gene Ontology:
Molecular function: protein binding; androgen binding; steroid binding
Cellular component: extracellular exosome; extracellular region
Genetic constraint (gnomAD): Loss-of-function variants: 37 observed, 44.4 expected, observed/expected ratio (o/e) 0.83, 90% interval 0.64 to 1.1. The upper end of that interval is the gene's LOEUF score, 1.1, which puts it in group 4 of 6, group 1 being the genes least tolerant of losing a copy. Missense variants: 466 observed, 525.02 expected, observed/expected ratio (o/e) 0.89, 90% interval 0.82 to 0.96. Synonymous variants: 217 observed, 217.02 expected, observed/expected ratio (o/e) 1, 90% interval 0.89 to 1.12.
Homologues: Orthologues: chimpanzee SHBG (99% identical), macaque SHBG (94% identical), rabbit SHBG (78% identical), dog SHBG (76% identical), guinea pig SHBG (70% identical), rat Shbg (67% identical), mouse Shbg (66% identical), tropical clawed frog shbg (30% identical). Paralogues in human: PROS1 (24% identical).
Diseases named in the same sentence as SHBG in open-access papers:
SHBG is named in the same sentence as 320 diseases in open-access papers, as found by Europe PMC text mining. Sharing a sentence is not in itself a finding about the gene and the disease. The quoted sentences say what the papers report.
Insulin resistance (496 papers, 2005 to 2026). Increased resistance towards insulin, that is, diminished effectiveness of insulin in reducing blood glucose levels. "Low serum SHBG levels are often detected in patients with metabolic disorders, indicating close associations of SHBG with insulin resistance and lipid dysregulation." (PMID 40625923, 2025). "In women, serum SHBG was further responsible for 19 % (p < 0.001) of the variation in insulin sensitivity, with low SHBG being associated with insulin resistance." (PMID 40532849, 2025). "The hyperinsulinemia caused by insulin resistance in obese patients also reduces the secretion of sex hormone-binding globulin by the liver." (PMID 41327353, 2025). "A somewhat weaker causal interplay of SHBG with insulin resistance and T2DM has been observed in Mendelian randomization studies." (PMID 40217583, 2025). "The most established link between SHBG and metabolic health is its inverse association with insulin resistance." (PMID 41180177, 2025). "Insulin resistance is also associated with decreased concentrations of sex hormone binding globulin (SHBG), resulting in an increased availability of sex steroids." (PMID 41291865, 2025). "A review further reported that the inverse association between SHBG and insulin resistance was stronger in women than in men." (PMID 40362793, 2025). "Hyperinsulinemia, which is a hallmark of insulin resistance, suppresses SHBG synthesis, creating a cycle of increasing free sex steroid concentrations and worsening metabolic outcomes." (PMID 41180177, 2025). "In women, high serum SHBG concentrations were strongly associated with low in vivo Homeostatic Model Assessment for Insulin Resistance (HOMA-IR), and lower unstimulated ex vivo lipolysis but higher isoprenaline stimulated ex vivo lipolysis." (PMID 40532849, 2025). "Reduced SHBG contributes to ovarian dysfunction, insulin resistance, and cardiovascular risk in PCOS." (PMID 40385768, 2025). "Recent research has also shown that low DHA levels are associated with reduced SHBG and increased insulin resistance." (PMID 41464800, 2025). "Low SHBG levels—a characteristic feature of hyperandrogenism in PCOS—are strongly associated with insulin resistance." (PMID 41464800, 2025). "Sedentary behavior exacerbates risk by reducing sex hormone-binding globulin levels, elevating free estradiol, and promoting insulin resistance and systemic inflammation—all of which synergize with estrogenic signaling to drive endometrial neoplasia." (PMID 41301707, 2025). "This indicates that after determining the risk of insulin resistance based on the TyG index, insulin resistance should be confirmed using HOMA-IR or SHBG, eventually." (PMID 40430120, 2025). "Of note, circulating SHBG levels are inversely associated with obesity, insulin resistance, metabolic syndrome, type 2 diabetes, and gestational diabetes." (PMID 40149685, 2025). "Lower circulating SHBG levels have been correlated with markers of metabolic dysregulation, suggesting its possible utility as a biomarker for hyperinsulinaemia, insulin resistance and metabolic dysfunction-associated steatosis liver disease (MASLD)." (PMID 41586225, 2025). "Low SHBG levels are associated with insulin resistance (IR).Specific single nucleotide polymorphisms (SNPs) in the SHBG gene are linked to IR." (PMID 39411775, 2024). "Low serum SHBG levels, associated with metabolic abnormalities and insulin resistance, are detected not only in the liver but also in various tissues of the female reproductive tract." (PMID 39006368, 2024). "SHBG has been observed to be negatively associated with insulin resistance, type 2 diabetes and gestational diabetes (a cause of higher mean birth weight) even after adjusting for BMI." (PMID 38225564, 2024). "An inverse association has been shown between SHBG levels and insulin resistance and metabolic syndrome." (PMID 38410430, 2024).
Insulin resistance (continued). "Alike PPARγ, low SHBG levels have been correlated with insulin resistance and associated endocrine abnormalities." (PMID 38874666, 2024). "Weight loss has been shown to increase SHBG, lower free androgens, and improve cardiometabolic risk factors including insulin, insulin resistance, and cholesterol levels." (PMID 38446316, 2024). "A decrease in SHBG levels was identified as an independent risk factor for insulin resistance in women with GDM." (PMID 38892323, 2024). "In women with polycystic ovarian syndrome, a condition associated with insulin resistance and an increased risk of type 2 diabetes mellitus, SHBG concentrations are decreased." (PMID 39014506, 2024). "Testosterone and sex hormone binding globulin (SHBG) have been associated with insulin resistance, a well-known condition in uremia." (PMID 39014506, 2024). "Low levels of SHBG (sex hormone binding globulin), which are also closely interrelated with LH levels, are also associated with increased insulin resistance and therefore with the occurrence of GDM." (PMID 39639281, 2024). "SHBG was also associated with higher insulin sensitivity and β-cell function and inversely associated with insulin resistance ∼3 years later." (PMID 39055720, 2024). "Findings from a large systematic review and meta-analysis of observational studies indicated that lower levels of SHBG are associated with insulin resistance and higher risk of T2D, with stronger associations seen in women compared to men." (PMID 38954350, 2024). "Low SHBG levels are linked to insulin resistance, hyperinsulinaemia, hyperglycaemia and obesity, which are potential predictors of the development of GDM." (PMID 39876919, 2024). "Studies show that weight loss improves many factors, such as lipid profile and insulin resistance, and increases sex hormone-binding globulin (SHBG) concentration." (PMID 38672240, 2024). "In the same context, sex hormone binding globulin (SHBG), a plasma transporter of sex steroids, is also associated with the metabolic syndrome and with insulin resistance." (PMID 39014506, 2024). "SHBG expression has been linked to PI3K/AKT pathway function in a human cellular model of insulin resistance and to inhibition of hepatic lipogenesis in mouse models by reducing PPARγ activation." (PMID 39409124, 2024). "Other findings indicated on the loss in SHBG protein in the course of insulin resistance and metabolic syndrome, which stays in line with the present investigation, where a marked SHBG protein downregulation has been observed in EMS SAT biopsies SHBG." (PMID 38146533, 2023). "It is well known that many men who present with adult-onset testosterone deficiency have a low level of SHBG associated with obesity, insulin resistance and type 2 diabetes." (PMID 37367840, 2023). "Lower levels of SHBG are mostly mediated by elevated levels of circulating insulin linked to the insulin resistance of obesity." (PMID 38203349, 2023). "Previous studies report that low SHBG is associated with obesity, insulin resistance and increased risk of metabolic diseases, such as diabetes." (PMID 37208559, 2023). "Insulin resistance and hyperinsulinemia cause decreased synthesis and production of SHBG by inhibiting hepatocyte nuclear factor 4α (HNF-4α) expression in the liver." (PMID 38044448, 2023). "This study showed that low SHBG in early pregnancy, which reflects the degree of insulin resistance, was associated with early‐onset GDM and with the need of long‐acting insulin treatment, which is mostly used for fasting hyperglycaemia." (PMID 36484476, 2023). "30.2% of women with PCOS developed GDM, and higher body mass, insulin resistance, fasting plasma glucose, elevated blood pressure, free androgen index, abnormal cholesterol, less gestational weight gain, and lower levels of SHBG were found to be risk factors." (PMID 38234933, 2023).
Insulin resistance (continued). "Metabolic abnormalities, including insulin resistance and reduced sex hormone-binding globulin (SHBG) concentrations, have been implicated in PCOS." (PMID 37015099, 2023). "Low serum SHBG levels are considered a biomarker of metabolic abnormalities and are associated with insulin resistance as hyperinsulinaemia inhibits hepatic SHBG production." (PMID 37015099, 2023). "The inverse association of SHBG with BMI has been related to underlying central adiposity, with insulin resistance and/or hepatic lipogenesis affecting liver synthesis of SHBG." (PMID 37639720, 2023). "Sex hormone-binding globulin (SHBG), which primary role is to bind testosterone, was inversely associated with insulin resistance, inflammation, diabetes, and metabolic syndrome." (PMID 36362788, 2022). "Low SHBG levels are correlated with low free testosterone even after HOMA-IR adjustment, suggesting that SHBG can be associated with testosterone deficiency beyond the influence of insulin resistance." (PMID 36231474, 2022). "Adipocyte hypertrophy is associated with AT dysfunction and insulin resistance, which, e.g., suppresses the serum concentration of SHBG thereby increasing the systemic concentrations of bioavailable oestrogen and testosterone." (PMID 36558416, 2022). "Decreased SHBG levels have been observed in patients with insulin resistance-associated diseases, including type 2 diabetes, MAFLD and PCOS." (PMID 35885586, 2022). "Androgen excess is caused or exacerbated by insulin resistance in at least two ways: by promoting increased ovarian androgen production and by suppressing hepatic SHBG synthesis." (PMID 36140452, 2022). "SHBG is known to be a strong independent marker of insulin resistance and T2DM risk, and its level is negatively associated with the lowering of fasting plasma glucose levels." (PMID 35628921, 2022). "The presence of moderate obesity also causes reductions in total testosterone levels, as a consequence of reductions in SHBG, due to insulin resistance-associated mechanisms and obesity-associated hyperinsulinemia." (PMID 36120442, 2022). "Lower circulating SHBG levels are associated with insulin resistance and it is well documented that SHBG levels increase after bariatric surgery." (PMID 34685777, 2021). "Subsequent MR analysis suggests a causal role for BMI and SHBG and a suggestive causal effect of insulin resistance on PCOS." (PMID 34207127, 2021). "It is worth mentioning that reduced SHBG levels are associated with insulin resistance and obesity due to hyperinsulinemia, which decreases the liver synthesis of SHBG." (PMID 34830515, 2021). "In another cross-sectional study of 350 Finnish men, sex hormone-binding globulin (SHBG) was proved to have an association with insulin resistance independent of testosterone, which nullified the association of total testosterone with insulin resistance." (PMID 34381648, 2021). "In the present study and in line with previous literature, SHBG was associated inversely with insulin resistance, insulin secretion, and AGM, independently of BMI." (PMID 34153097, 2021). "The logistic regression analysis showed that SHBG was associated with insulin-resistance and atherogenic dyslipidemia, independently of BMI." (PMID 34089497, 2021). "In obesity, low SHBG is implicated in increasing insulin resistance and cardiovascular risk and is suggested to be a marker of abdominal obesity." (PMID 34877821, 2021). "In pathological conditions with reduced circulating SHBG levels—such as obesity or insulin resistance—the symptoms of testosterone deficiency in men can be exacerbated." (PMID 34335746, 2021). "Previous work has suggested that a low sex hormone-binding globulin (SHBG) concentration associates with insulin resistance." (PMID 34386722, 2021). "Lower SHBG levels are associated with insulin resistance, thus rendering this protein an important metabolic marker of increased risk for diabetes." (PMID 33918160, 2021).
Insulin resistance (continued). "High AGE levels are associated with increased insulin resistance, that in turn, drives sex-hormone binding globulin (SHBG) reduction and androgen excess." (PMID 34204057, 2021). "Given that obesity is intimately associated with SHBG levels, insulin resistance, and inflammation markers, we analyzed SHBG correlations with all measured parameters only in prepubertal children with obesity to avoid this confounding factor." (PMID 33689083, 2021). "The excess visceral fat also causes insulin resistance as well as an increase in insulin levels, which decrease SHBG production in the liver, leading to higher levels of E2." (PMID 34940598, 2021). "In women, increased testosterone levels are associated with lower SHBG, as well as with dyslipidemia and insulin resistance." (PMID 33854482, 2021). "The inverse-variance-weighted method suggests a causal effect of SHBG, BMI, WC, and insulin resistance." (PMID 34207127, 2021). "Insulin is a growth factor, and hyperinsulinemia present in insulin resistance is associated with lower levels of sex hormone binding globulin, thereby increasing the availability of unbound free androgens." (PMID 33562646, 2021). "Our results suggested the association between SHBG and glycemic control dependeding on the BMI, and SHBG cannot reflect insulin resistance for women with PCOS." (PMID 33101409, 2020). "Interest in SHBG has increased in recent years because lower circulating levels of SHBG are inversely associated with obesity, insulin resistance (measured by HOMA-IR), metabolic syndrome, type 2 diabetes, and gestational diabetes." (PMID 33139661, 2020). "In our study, another predicting factor of WBC was SHBG, which is commonly associated with insulin resistance but also for diabetes type II and hypertension." (PMID 32219132, 2020). "A genetic study also found weaker causal effects of SHBG for insulin resistance and diabetes, suggesting that the observational associations are partly confounded rather than conferred directly via circulating SHBG." (PMID 33101409, 2020). "Insulin resistance leads to hyperinsulinemia, which in turn causes reproductive dysfunction by down-regulating SHBG production." (PMID 33139661, 2020). "Multivariate regression analysis indicated that sex hormone-binding globulin (SHBG) concentrations (p = 0.002) and insulin resistance (p = 0.008) were factors associated with discrepant IA values." (PMID 33352636, 2020). "This evidence comes mainly from cross-sectional investigations in peripubertal children, and studies that have found weight loss to be associated with decreased insulin resistance and increase in serum SHBG level." (PMID 30925463, 2019). "The aim of this study was to investigate bidirectional associations between SHBG and insulin resistance (HOMA-IR) and adiposity from childhood to early adulthood." (PMID 30925463, 2019). "In the present study, we investigated bidirectional associations between serum SHBG, adiposity and insulin resistance at five time points in females transitioning from pre-puberty to early adulthood using a cross-lagged panel model analysis." (PMID 30925463, 2019). "Bivariate cross-lagged path analysis was used to explore the direction of the associations between SHBG, adiposity and insulin resistance, which allows examining temporal associations better than simple regression analysis." (PMID 30925463, 2019). "Obesity is associated with hyperinsulinemiaand insulin resistance causing an increasedhormonal ovarian production and a reduced synthesisof sex hormone-binding globulin (SHBG), with subsequenthyperandrogenism." (PMID 31310072, 2019). "Longitudinal studies that have assessed temporal associations between SHBG, adiposity and insulin resistance from childhood to adulthood are few and far between." (PMID 30925463, 2019).